CRP (C-reactive protein)
Diseases named in the same sentence as CRP in open-access papers (continued):
Sharing a sentence is not in itself a finding about the gene and the disease.
scoliosis (7 papers, 2017 to 2025). A congenital or acquired spinal deformity characterized by lateral curvature of the spine. "However, evidence regarding the diagnostic value of CRP for early detection of SSI after pediatric scoliosis correction remains scarce." (PMID 41226908, 2025). "Future prospective studies with larger SSI cohorts are needed to validate the predictive value of CRP in scoliosis surgery." (PMID 41226908, 2025). "For TDL patients, we observed that Patients with high BMI, a higher proportion of spinal scoliosis, and abnormal elevation of CRP levels were more likely to have reduced FVC." (PMID 38914991, 2024). "In TDL patients, we observed that Patients with high BMI, a higher proportion of spinal scoliosis, and abnormal elevation of CRP levels were more likely to have reduced FVC." (PMID 38914991, 2024). "This study aimed to determine connection between OPRM1 and rs1205 CRP SNPs in pediatric patients postoperatively and pain intensity, the opioid dose needed to control pain after scoliosis correction, and other clinical aspects." (PMID 38137077, 2023). "The aim of this article is to investigate whether the OPRM1 A118G and rs1205 CRP SNPs influence the perception of pain and the need for opioid analgesics immediately after orthopedic correction of scoliosis in a group of patients under 18 years of age." (PMID 38137077, 2023). "Among scoliosis patients, CAR and CRP values were significantly higher in patients with a Cobb angle >20° compared with those with the angle of 11-20° (P < 0.001 for all)." (PMID 41200945, 2025). "Compared with controls, the scoliosis group had significantly higher WBC, neutrophils, lymphocytes, monocytes, CRP, NLR, CAR, and phosphorus (P < 0.01 for all)." (PMID 41200945, 2025). "While CRP monitoring is commonly used after major orthopedic procedures such as joint arthroplasty, its utility for early SSI detection after scoliosis surgery remains unclear." (PMID 41226908, 2025). "Although CRP is a commonly used marker of postoperative inflammation, this study shows that it is not reliable as a standalone tool for early detection of surgical site infection (SSI) following scoliosis correction." (PMID 41226908, 2025). "An additional analysis was performed to compare serum CRP concentrations between patients who did not develop an SSI and those who did, regardless of scoliosis type (idiopathic or non-idiopathic)." (PMID 41226908, 2025). "In our cohort of scoliosis patients who subsequently developed SSI, the CRP trajectory between POD 2/3 and POD 4/5 was not indicative of infection." (PMID 41226908, 2025). "More recently, the C-reactive protein/albumin ratio (CAR) has gained attention as a novel biomarker in oncology, cardiovascular disease, and autoimmune disorders, though it has not yet been evaluated in scoliosis." (PMID 41200945, 2025).
Tinnitus (7 papers, 2022 to 2025). Tinnitus is an auditory perception that can be described as the experience of sound, in the ear or in the head, in the absence of external acoustic stimulation. "A further immune system marker, which is related with chronic stress and is, therefore, highly relevant for studying the associations between chronic stress and inflammation in tinnitus, is C-reactive protein (CRP)." (PMID 35493955, 2022). "The aim of our study was to investigate the association between resting state MEG brain activity and CRP levels in chronic tinnitus." (PMID 35493955, 2022). "We suggest that higher CRP levels and the associated deactivation of the orbitofrontal cortex in chronic tinnitus patients is maintaining the tinnitus percept through disinhibition of the auditory cortex and attentional or emotional top-down processes." (PMID 35493955, 2022). "Both directions are conceivable, i.e., inflammation could either cause or exacerbate the tinnitus symptoms, or intrusive tinnitus could raise CRP levels." (PMID 35493955, 2022). "Interestingly, perceived stress was significantly higher in the tinnitus group compared to the control group and an association between CRP and PSS score was only found in the tinnitus group (as well as in the pooled sample)." (PMID 35493955, 2022). "Peripheral inflammatory markers, such as significantly lower C-reactive protein (CRP) and IL-10 levels and higher oxidative stress indices and total oxidant statuses, have been reported in tinnitus patients than in healthy controls." (PMID 40881791, 2025). "In tinnitus, the relevant protein (C-reactive protein; CRP) was found to be negatively correlated with gamma power in the orbitofrontal cortex, meaning that higher CRP levels were associated with decreased activity in the orbitofrontal cortex." (PMID 38015287, 2023). "The authors concluded that higher CRP levels and the deactivation of the orbitofrontal cortex are responsible for maintaining tinnitus perception by disinhibiting the auditory cortex." (PMID 38015287, 2023). "Our findings indicate that people with chronic tinnitus have higher CRP levels than healthy controls, which makes them particularly vulnerable." (PMID 35493955, 2022). "This notion is supported by a study showing that taking Naltrexone, which reduces CRP levels and acts on μ-opioid receptors in the orbitofrontal cortex (amongst other regions) led to a significant reduction of tinnitus distress." (PMID 35493955, 2022). "Overall, CRP levels were significantly increased in tinnitus compared to the control group." (PMID 38015287, 2023). "Moreover, CRP levels were significantly higher in the tinnitus group than in the healthy controls (p = 0.045)." (PMID 35493955, 2022). "Although the direction of the association (i.e., causation) between CRP levels and orbitofrontal gamma power in chronic tinnitus is not yet known, inflammation reducing interventions are promising candidates when developing treatments for tinnitus patients." (PMID 35493955, 2022). "By the 12-week follow-up, hs-CRP and ESR levels had decreased, and the patient reported improvement in tinnitus frequency and dizziness." (PMID 39744176, 2025). "Some previous studies have indicated that CRP levels are not significantly elevated in individuals with tinnitus." (PMID 40558411, 2025). "We found a significant negative correlation between high gamma and CRP levels in the BA11 lateral cluster for the tinnitus group." (PMID 35493955, 2022). "We found a significant negative correlation between CRP and gamma power in the orbitofrontal cortex in tinnitus patients (p < 0.001), pointing to a deactivation of the orbitofrontal cortex when CRP was high." (PMID 35493955, 2022).
toxicity (7 papers, 2022 to 2025). The degree to which an agent can damage an organism. "Among the laboratory parameters, we found that low lymphocytes, low monocytes, high CRP levels, and a high CRP-to-lymphocyte ratio (CLR) were associated with lung toxicity (p = 0.023; p = 0.024; p = 0.036; and p = 0.011, respectively)." (PMID 40731887, 2025). "Radiotherapy‐induced CRP can increase the risk of skin toxicity and cardiac morbidity, and ischaemic heart diseases." (PMID 35178859, 2022). "For OS, the models highlighted similar contributors, with ISUP grade group, electrolyte disturbances, increased ALP, liver toxicity, and elevated CRP showing the strongest impact on predicted shorter survival." (PMID 41375007, 2025). "Co-administration of DTG-based therapy and isoniazid results in significantly elevated levels of inflammatory markers such as c-reactive protein, interferon-γ, CXCL10, and other cytokines which result into liver toxicity." (PMID 35366917, 2022).
vitiligo (7 papers, 2016 to 2024). Generalized well circumscribed patches of leukoderma that are generally distributed over symmetric body locations and is due to autoimmune destruction of melanocytes. "The studies consistently found that CRP levels were elevated in vitiligo patients compared to the control group." (PMID 38606245, 2024). "Our study also found that CRP levels were significantly higher in vitiligo patients compared to controls." (PMID 38606245, 2024). "Whereas CRP was significantly higher in active (range = 2.0–7.2, mean = 4.46 ± 1.09) than in stable vitiligo (range = 1.6–6.7, mean = 3.75 ± 1.08) (p < 0.05)." (PMID 37762802, 2023). "In both active and stable vitiligo, CRP and IL-15 were significantly higher than controls (p < 0.05)." (PMID 37762802, 2023). "This study found that MHR and CRP values were higher in vitiligo patients as compared to controls." (PMID 38606245, 2024). "This study found that MHR and CRP values were higher in vitiligo patients." (PMID 38606245, 2024). "Unlike previous studies, we do not consider CRP to be a reliable marker for indicating the severity of vitiligo or monitoring treatment response due to the presence of lots of confounding factors." (PMID 38606245, 2024). "Higher levels of neutrophil/lymphocyte ratio, C-reactive protein, and inflammatory cytokines/chemokines were documented in vitiligo patients when compared to the control group (non-significant)." (PMID 37985303, 2024). "Furthermore, higher levels of CRP, IL-15, CXCL9, and CXCL10 are identified in active vitiligo." (PMID 37762802, 2023).
acromegaly (6 papers, 2015 to 2025). Acromegaly is an acquired disorder related to excessive production of growth hormone (GH) and characterized by progressive somatic disfigurement (mainly involving the face and extremities) and systemic manifestations. "Interestingly, CRP has been found to be reduced in active acromegaly despite the high risk of cardiovascular outcomes among acromegaly patients." (PMID 31396153, 2019). "Possibly, a lower hs-CRP may be linked to lower than expected prevalence of atherosclerosis in patients with active acromegaly, despite the presence of other risk factors such as insulin resistance and hypertension." (PMID 24972804, 2015). "Indeed, CRP is significantly reduced in acromegaly, a state of GH hypersecretion." (PMID 36183116, 2022). "CRP levels increase following IGF-1 lowering therapy, and controlled acromegaly patients display similar levels as healthy controls." (PMID 32458292, 2020).
acute leukemia (6 papers, 2021 to 2025). A clonal (malignant) hematopoietic disorder with an acute onset, affecting the bone marrow and the peripheral blood. "In univariate and multivariate analyses, elevated triglyceride and high-sensitive C-reactive protein (HS-CRP) were significantly associated with a diagnosis of acute leukemia in MDS patients." (PMID 36114519, 2022). "The study identified a strong correlation between elevated CRP levels and the risk of BIFI in pediatric acute leukemia patients, suggesting that CRP can serve as a valuable predictive biomarker for these infections." (PMID 39720656, 2024). "We calculated the sensitivity, specificity, positive predictive and negative predictive values of cut-off values for the PSPN, PCT and CRP that were useful for distinguishing septic febrile neutropenia in acute leukemia patients." (PMID 34324506, 2021). "This study aims to determine the role of procalcitonin (PCT) and presepsin (PSPN) in infectious complication in comparison to C-reactive protein (CRP) on the first and third day at the onset of febrile neutropenia in patients with acute leukemia." (PMID 34324506, 2021). "While this investigation focuses on a pediatric cohort of patients with acute leukemia, it has demonstrated that PSP, in conjunction with CRP and PCT, possesses the capability to differentiate between various bacterial infections, notably Gram-negative bacteremia." (PMID 40217689, 2025).
acute tonsillitis (6 papers, 2019 to 2025). An acute inflammation of the tonsils caused by viruses or bacteria. "When looking at the subgroup of patients who suffered from chronic pain preoperatively, a significant moderate positive relationship between CRP and the strength of preoperative chronic pain was shown for the diagnosis of recurrent acute tonsillitis." (PMID 37079072, 2023). "A study from Denmark investigated 100 patients 15–40 years of age who had acute tonsillitis and found significantly elevated mean values of CRP, WBC, and absolute neutrophil count in patients with GABHS compared with patients without GABHS." (PMID 31428594, 2019). "When looking at the subgroup of patients who suffered from chronic pain preoperatively, a significant moderate positive relationship (r = 0.49; p = 0.02) between CRP and the strength of preoperative chronic pain was shown for the diagnosis of chronic tonsillitis." (PMID 37079072, 2023). "However, CRP was 0.19 ± 0.30 in patients with chronic tonsillitis." (PMID 33490647, 2021). "In a prior study, the CRP and LEUK values in case of recurrent acute tonsillitis were very normal in most cases compared to the pathologically high values in case of a peritonsillar abscess." (PMID 37079072, 2023). "CRP and ESR are the most important parameters in confirming a diagnosis and distinguishing PFAPA from acute tonsillitis." (PMID 37428978, 2023).
age (6 papers, 2021 to 2025). A temporal measurement of the time period elapsed since an identifiable point in the life cycle of an organism. "Inflammatory markers such as CRP and IL-6 are reported to be associated with decreased muscle mass and strength, and the reduction of inflammation is believed to directly or indirectly ameliorate age-related muscle loss." (PMID 33882026, 2021). "Thus, based on these results, we recommend the use of WBCs and CRP in AGE cases presenting to the ED to aid and facilitate proper disposition and management." (PMID 40426796, 2025). "Inflammatory markers, such as C-reactive protein (CRP) and procalcitonin (PCT), have emerged as valuable tools in the clinical decision-making process, providing critical insights into the severity of inflammation and guiding treatment strategies for pediatric patients presenting with AGE." (PMID 40426796, 2025).
agoraphobia (6 papers, 2015 to 2025). An anxiety disorder characterized by an intense, irrational fear of venturing out into open places or situations in which help (or escape) might not be available should excessive anxiety or panic symptoms develop. "Associations between lifetime agoraphobia status at baseline and inflammatory measures (C-reactive protein) at follow-up, serially adjusted for covariates." (PMID 25875094, 2015). "Significant increases in c-reactive protein and tumor necrosis factor alpha levels were also observed in patients with agoraphobia over time." (PMID 32906843, 2020). "Individuals with agoraphobia had significantly higher follow-up levels of C-reactive protein (p = 0.007) and tumor-necrosis-factor-α (p = 0.042) as well as lower levels of the cardioprotective marker adiponectin (p = 0.032) than their non-agoraphobic counterparts." (PMID 25875094, 2015). "The composite score of proinflammatory markers (including CRP, IL-6 and TNF-α) at follow-up was higher (model 5: β = 0.578 (95%-CI 0.241–0.915) among subjects suffering from lifetime agoraphobia at baseline." (PMID 25875094, 2015).
alcoholic liver diseases (6 papers, 2020 to 2023). A disorder caused by damage to the liver parenchyma due to alcohol consumption. "The only factor associated with CRP changes was the presence of alcoholic liver disease (p = 0.038)." (PMID 32127631, 2020). "We confirmed significant decreases in GGT and hs-CRP levels in male subjects suspected of non-alcoholic liver disease as a result of supplementation with 125 mg of GBCK25 (low dose)." (PMID 32425736, 2020).
allergic asthma (6 papers, 2015 to 2025). A asthma with a basis in a pathological type I hypersensitivity reaction. "This suggests that as IgE levels increase, CRP levels also tend to increase, demonstrating a significant association between these biomarkers in the context of allergic asthma and HFrD." (PMID 39201554, 2024). "We also demonstrated a significant association between serum total IgE and serum CRP values in the context of allergic asthma and HFrD." (PMID 39201554, 2024). "This indicates that neutrophils, leukocytes, and CRP are associated with the severity of allergic asthma, however, they present only certain pathophysiological aspects of the disease and are insufficient for a comprehensive and precise evaluation of its severity." (PMID 41458088, 2025). "In a recent study, we analyzed the correlation between IgE and CRP levels in rats with allergic asthma induced by ovalbumin, ragweed and/or house dust mites, combined with a HFrD (with 40% fructose in drinking water)." (PMID 39683498, 2024). "Therefore, CRP could be a valuable indicator for detecting systemic inflammation in allergic asthma." (PMID 39201554, 2024). "Indicators such as neutrophils, leukocytes, and C-reactive protein (CRP) hold significant clinical relevance in the diagnosis and severity assessment of allergic asthma." (PMID 41458088, 2025). "The current findings demonstrate that sensitization and challenges with OVA significantly elevated CRP levels compared to the control group (A: 978.3 ± 96.8 μg/mL vs. C: 413.2 ± 117.7 μg/mL, p < 0.001), suggesting that CRP could serve as a marker for systemic inflammation in allergic asthma." (PMID 39683498, 2024). "In addition, it has been noted that levels of C reactive protein (CRP) are increased in non-allergic but not in allergic asthma conditions." (PMID 26289385, 2015).
alopecia (6 papers, 2019 to 2025). Hair loss usually from the scalp. "rs4945 was associated with the erythrocyte sedimentation rate and rs1878327 was associated with alopecia, C-reactive protein, complement 3, anti-dsDNA antibody, and high disease activity." (PMID 31811237, 2019). "The severity of inflammation could also play a role as suggested by the higher levels of CRP and platelets among patients with alopecia." (PMID 35341398, 2022). "SALT: Severity of Alopecia Tool; ALT: alanine aminotransferase; AST: aspartate aminotransferase; CRP: C-reactive protein; IGRA: interferon gamma release assay; CPK: creatine phosphokinase." (PMID 41216101, 2025).
angioedema (6 papers, 2019 to 2026). Swelling involving the deep dermis, subcutaneous, or submucosal tissues, representing localized edema. "Additional proposed markers include C-reactive protein (CRP), which correlates with disease activity and severity, and D-dimers, which are elevated in severe cases and associated with recurrent angioedema." (PMID 40933429, 2025). "Patients with angioedema had higher CRP (p = 0.038) and UAS7 scores (p < 0.001)." (PMID 42072774, 2026). "Baseline disease activity assessment, which considers the presence of angioedema and disease activity scores, gender, and CRP levels might be helpful to predict treatment outcomes in CSU patients and to choose the right treatment for each patient." (PMID 35853771, 2022). "For the ultimate care of patients, determining disease activity at baseline and paying attention to the laboratory markers such as CRP, total IgE and IgG-anti-TPO as well as clinical markers such as female gender and angioedema might be of special importance." (PMID 35853771, 2022).
anterior uveitis (6 papers, 2015 to 2023). Inflammation of the iris and anterior chamber of the eye. "Earlier investigations showed that ESR and CRP are within the normal range in a majority of patients with anterior uveitis." (PMID 30411142, 2019). "A recent study suggested that the acute phase response protein c-reactive protein (CRP) in serum could be an indicator of the degree of inflammation in anterior uveitis." (PMID 34212267, 2021). "The serum HMGB1 of AS patients was significantly higher than in healthy controls and positively correlated with BASDAI, BASFI, ASDAS-ESR, ASDAS-CRP, ESR, and CRP, but not with HLA-B27, anterior uveitis, and recurrent diarrhea." (PMID 27800496, 2016).